HIF1A (hypoxia inducible factor 1 subunit alpha)
Diseases named in the same sentence as HIF1A in open-access papers (continued):
Sharing a sentence is not in itself a finding about the gene and the disease.
infection (continued). "However, whether HIF1α-dependent glycolysis is critical for macrophage polarization during in vivo infection with different pathogenic microorganisms remains uninvestigated." (PMID 29483608, 2018). "Mechanistically, the differential ability of certain Leishmania species to interfere with NF-κB activation might underlie the divergent ability of different Leishmania species to block infection-associated inflammatory HIF-1α-accumulation under normoxic conditions." (PMID 29520262, 2018). "Because HIF-1α is upregulated during the differentiation of monocytes to macrophages, we were intrigued to know whether HIF-1α would play a role in resistance/susceptibility to infection if we kept M-CSF in the medium during infection with L. donovani to allow differentiation into macrophages." (PMID 28892492, 2017). "Thus, it may be hypothesized that stabilization of HIF-1α might facilitate formation of ETs in myeloid cells in hypoxic or iron-deficient tissue as it occurs during infection." (PMID 27129288, 2016). "Consequently, we next sought to determine whether activation of HIF1α was inhibited under conditions known to enhance susceptibility to A. fumigatus pulmonary growth and infection." (PMID 25255025, 2014). "Therefore, we hypothesized that HIF-1α is stabilized during infections with RSV and may contribute to RSV-associated changes in gene expression." (PMID 18839041, 2008). "We show that HIF-1α can bind to viral promoters and induce lytic genes only during this early window of infection, before the KSHV genome undergoes heterochromatinization and establishes latency." (PMID 41805195, 2026). "Considering that PEDV infection activated HIF-1α and induced mitochondrial damage, here we further examined intracellular mROS accumulation upon infection." (PMID 41512444, 2026). "Mechanistic studies show that C. atrati extracts and purified 4′HAP exert strong anti-parasitic effects by selectively activating GSK3β, which in turn destabilizes HIF-1α under infection conditions." (PMID 41509906, 2026). "While, the hydroxylated HIF1α showed inverse correlation with the ROS in these mutant cells after 12 and 18 hrs infection under normoxia, indicating an inhibitory effect of ROS on the PHD2 that hydroxylate HIF1α." (PMID 40570045, 2025). "In contrast, HIF-1α-specific target genes including Nos2, Pgk1 and Ldha are dramatically increased upon infection, and these are predominantly expressed in monocyte-derived macrophages." (PMID 40191198, 2025). "Based on these, we assume that STING regulates host metabolic reprogramming through HIF1α, a major transcription factor activated in response to infection, enabling the cells to meet the increased metabolic demands." (PMID 40387431, 2025). "The Warburg effect is regulated by hypoxia-inducible factor 1 (HIF-1α), which is activated by growth factors, hypoxia, and infections." (PMID 40017802, 2025). "By inhibiting STING, it potentially reduces HIF1α-driven glycolysis by decreasing mROS production, resulting in less inflammatory damage during infection." (PMID 40387431, 2025). "HIF-1α activation during infections enhances immune responses by promoting inflammation and antimicrobial activity." (PMID 40731804, 2025). "Western blot results showed that infection significantly upregulated the expression of HIF-1α and IL-1β, suggesting activation of hypoxic stress and the NF-κB pathway." (PMID 40867552, 2025). "Co-immunoprecipitation (Co-IP) analysis further revealed that infection with N. caninum decreased the ubiquitination of HIF-1α." (PMID 40307939, 2025). "Here, we identified HIF1α and Blimp-1 as key regulators of Areg in Treg cells during infection, with HIF1α acting independently of TIGIT." (PMID 41094201, 2025). "This is consistent with an additional study investigating initial transcriptomic changes after in vitro L. major infection, reporting HIF-1α signaling is enriched in murine macrophages at 4 hours post-infection." (PMID 40191198, 2025).
infection (continued). "Infection of crypt-like intestinal epithelial cells with diffusely adherent E. coli increases the expression of HIF-1α protein, leading to upregulation of VEGF-A expression and increased angiogenesis." (PMID 41249582, 2025). "In the immune response, HIF-1α modulates the expression of various cytokines and chemokines, which recruit immune cells to sites of infection or injury." (PMID 40443737, 2025). "During infection, it is delivered to the host cells via outer membrane vesicles, leading to the induction of hypoxia-inducible factor 1-alpha (HIF-1α) through TLR2 activation, thereby lowering levels of cyclin D1 and affecting cell cycle progression." (PMID 40679283, 2025). "Porcine reproductive and respiratory syndrome virus (PRRSV) infection elevates HIF1α expression and enhances viral replication." (PMID 39601573, 2025). "In this study, cardiac HIF-1α increased two-fold after 17 weeks of infection and this increase in HIF-1α was blunted in HIV-1-infected animals treated with DTG/TDF/FTC for thirteen weeks." (PMID 40332423, 2025). "This dual effect of HIF-1α—suppressing IL-12 while promoting IL-10—renders dendritic cells less effective in supporting T cell-mediated control of infection." (PMID 40512023, 2025). "As one of the subunits of HIF1, HIF1A participates in regulating various processes such as cellular metabolism, immune responses, anti-infection, and defense, making it an important transcription factor." (PMID 40427687, 2025). "HIF-1α has been reported to be one of the significant regulators of energy homeostasis and cellular adaptation to stress and infection with several intracellular pathogens (e.g. Bartonella henselae, T. gondii)." (PMID 40307939, 2025). "Considering that different environmental cues trigger HIF-1 signaling in immune cells, we examined HIF-1α expression in T cells following infection." (PMID 40590226, 2025). "We observed a significant correlation between Areg and both Hif1a and Prdm1 expression after infection, especially in Treg cells, and thus tested their impact on Areg induction following LCMV infection." (PMID 41094201, 2025). "This survival mechanism highlights the evolutionary conservation of HIF-1α-mediated metabolic adaptation in preserving lymphoid cell homeostasis during infection." (PMID 40791591, 2025). "For example, the vaccinia virus (VACV) can inhibit the PHD2-dependent hydroxylation pathway of HIF-1α by binding to PHD2 via the C16 protein post-organismal infection, expediting the rapid accumulation of HIF-1α." (PMID 38539163, 2024). "In a complementary approach, we performed indirect immunofluorescence microscopy of HSAEC1-KT cells to examine the protein levels and localization of HIF1α following in vitro infection with Mucorales." (PMID 38902255, 2024). "This study lays the foundation for further exploration into the potential systemic impact of the HIF1A/glycolysis axis within the realm of chronic inflammation contrasting with its role in a local setting during the acute phase of infection." (PMID 38922679, 2024). "Administration of inhibitors of NFATc1 and HIF-1α in infected mice depicted similar observations and justifies the role of these two transcription factors in IL-33 secretion and propagation of infection." (PMID 38750790, 2024). "Conversely, after inhibitor infection, Hif1a (p=0.048), Fzd6 (p<0.01), and Gcnt2 (p<0.01) were increased and Atg14 (p=0.042) increased." (PMID 38770735, 2024). "Infection with HIF-1α(+) reversed the downregulated expression of HIF-1α, and OPN, and the upregulated levels of α-SMA in VSMCs in the presence of PRMT3 deficiency." (PMID 38200452, 2024). "In view of the important role of HIF-1α in metabolism and immunity, we are interested in the role of HIF-1α in the infection of hypoxia-tolerant L. crocea by A. hydrophila." (PMID 39156889, 2024).
infection (continued). "Our previous analysis of the transcriptome response of A549 cells to infection with R. delemar, R. oryzae or M. circinelloides also predicted the activation of HIF1α signaling." (PMID 38902255, 2024). "The correlation between increased levels of HIF-1α and ongoing infection has been repeatedly reported in the literature." (PMID 39456823, 2024). "Increased accumulation of HIF1α protein also occurred following infection of HSAEC1-KT cells with Cunninghamella bertholletiae and Rhizopus oryzae." (PMID 38902255, 2024). "Western blot analysis was used to confirm the infection efficiency of Sh‐HIF‐1α and Sh‐EZH2, as well as the knockdown efficiency of Si‐ALKBH5 and Si‐YTHDF2." (PMID 38344897, 2024). "While HIF1α activation occurs in response to hypoxia and inflammatory signaling following infection, ARNT is constitutively expressed, and its regulation is less well characterized." (PMID 38897207, 2024). "HIF1A, a transcription factor that responds to low oxygen availability and plays a regulatory role in response to a variety of molecular signals of infection and inflammation and induce autophagy, is targeted by hsa-miR-20a-5p and hsa-miR-106b-5p in LP." (PMID 38343694, 2024). "HIF-1α is a heterodimeric protein complex that serves as a critical regulator of the cellular response to physiological hypoxia and infection, exerting diverse pathophysiological effects at the cellular, tissue, and organismal levels." (PMID 38539163, 2024). "Firstly, specific viruses can accumulate HIF-1α during infection through inducing the degradation of prolyl hydroxylase (PHD)." (PMID 38539163, 2024). "We found that SIRT1 knockdown showed increased acetylation of HIF1α in the infected macrophages in comparison to the scrambled infected control at 16 hr post-infection." (PMID 39693143, 2024). "Here, we found that infection of DCs with Mycobacterium tuberculosis (Mtb) triggers HIF1A-mediated aerobic glycolysis in a TLR2-dependent manner, and that this metabolic profile is essential for DC migration." (PMID 38922679, 2024). "These time points were selected to evaluate how HIF1a affects leukocyte responses during planktonic infection (day 3) versus mature biofilm formation (day 14)." (PMID 38421730, 2024). "In the M. marinum-zebrafish model, stabilization of HIF-1α at the early stages of infection enhanced the levels of nitric oxide and reduced mycobacterial burden." (PMID 39717773, 2024). "In contrast, HIF-1α knockdown was shown to ameliorate inflammation induced by PSCV infection in MH-S and THP-1 cells and decrease increased CTGF, COLA1, and α-SMA in CPMSCV-exposure MRC-5 cells." (PMID 38914619, 2024). "The protein levels of HIF-1α also increased significantly at 4–6-day post-infection in fish and at 48–72 h post-infection in cells." (PMID 38680083, 2024). "Specifically, studies have found that M. marinum infection of zebrafish induced HIF-1α-dependent transcription of Il1b, which then activated neutrophil-mediated production of nitric oxide and protection against infection." (PMID 39119289, 2024). "Remarkably, the entire assembly of host lncRNAs predominantly target three mRNAs over the first 5 days of infection: Plec (upregulated), Adar1 and Hif1α (both downregulated)." (PMID 39344634, 2024). "During pathogen infection, HIF-1α expression is upregulated in Th2 cells, thereby fostering their proliferation." (PMID 39575238, 2024). "To this end, we measured HIF1α accumulation following infections with each cell type on opposite sides of a Transwell membrane which would allow for diffusion of small molecules but prevent contact with R. delemar." (PMID 38902255, 2024). "We also provide evidence that the hypoxia inducible factor 1-alpha (HIF1α) signaling pathway is activated following in vitro infection with R. delemar and other Mucorales." (PMID 38902255, 2024).
infection (continued). "As predicted by our RNA-seq analysis, we observed an increase in HIF1α protein abundance following in vitro infection of HSAEC1-KT cells with R. delemar." (PMID 38902255, 2024). "Ruan and Zimna further demonstrated that HIF-1α activation promotes the production of inflammatory mediators, influencing immune cell function and enhancing the body’s response to pathogens during infection and inflammation." (PMID 39766299, 2024). "We also found that intervention of HIF-1α and VEGFA signaling affected infection outcomes caused by respiratory bacteria in mouse models." (PMID 36916939, 2023). "Infection with several viruses up-regulated HIF-1α protein levels because several virus proteins inhibited degradation of HIF-1α." (PMID 37615898, 2023). "This is in contrast to our observation in human and murine macrophages, where the infection resulted in augmented HIF1α levels, which impaired the activation of STAT3, resulting in inhibition of C. burnetii replication." (PMID 36793725, 2023). "As observed in our C57BL/6 mouse model, infection with H. pylori significantly increased levels of HIF-1α in foci of inflammation." (PMID 37828903, 2023). "Hypoxic molecule HIF-1α (stabilisation has antimicrobial activity) was also found to be decreased in the NCoR1 KD condition at 24 h post infection." (PMID 37590294, 2023). "The most predominant 2-OGDD involved in the metabolic response to infection are prolyl hydroxylases (PHDs), which under homeostatic levels of α-ketoglutarate and oxygen promote ubiquitination and targeted degradation of HIF-1α." (PMID 37417946, 2023). "The results are similar to the study of L. monocytogenes infection to Hela cells, which showed that the infection ability of L. monocytogenes to Hela cells was significantly decreased after inhibition of HIF-1α expression." (PMID 37681973, 2023). "In those studies, the primary mechanism by which HIF-1α stabilization contributed to the outcome of infection was via downregulation of the receptors required for viral entry (ACE2 and TMPRSS2), effectively limiting viral burdens." (PMID 37417946, 2023). "Hypoxia-inducible factor 1α (HIF-1α) Infection regulates H. capsulatum in mammals, being a key player in macrophage-mediated innate immunity." (PMID 37755037, 2023). "Activation of HIF-1α signaling is a common phenomenon to many human infections including bacterial, viral and intracellular parasites such as Leishmania amazonensis and Toxoplasma gondii." (PMID 36814444, 2023). "All of these findings suggest that HIF-1α and/or VEGFA represents a potential target to reduce the severity of infections caused by P. multocida." (PMID 36916939, 2023). "In our investigational analysis, we found a significant increase in HIF-1α mRNA expression and protein levels in the long-term post-infection group." (PMID 37626956, 2023). "Infections with P. multocida isolates from multiple hosts alter barrier functions and activate the HIF-1α–VEGFA pathway in human respiratory epithelial cells." (PMID 36916939, 2023). "Taken together, these data support the active manipulation of the HIF-1α/PHD–mediated metabolic outcomes during infection." (PMID 37417946, 2023). "HIF-1α was found to be activated in alveolar type 2 cells (the main target for SARS-CoV-2 at the early stage of infection) during acute lung injuries." (PMID 36983445, 2023). "Accumulating evidence from literature strongly suggest that HIF-1α plays a key role in the immune response to infection and inflammatory process in mammalian hosts." (PMID 37600803, 2023). "Induced pluripotent stem cell-derived cardiomyocytes (iPSC-CMs) also show significant enrichment for hypoxia-related genes upon infection with T. cruzi, including HIF-1α, VEGFB, HK2, SLC2A3, ENO1, and LDHA." (PMID 37375100, 2023). "At the later phase of infection, the level of HIF-1α decreases sharply, suggesting that Chlamydia employs other mechanisms to preserve the expression of MCL-1 during infection." (PMID 37374883, 2023).
infection (continued). "Several genes from the ‘Hypoxia signaling’ pathway, notably the hypoxia-inducible factor 1-α (HIF-1α) have been reported to be upregulated in human cardiomyocytes as a response to infection with T. cruzi." (PMID 38062533, 2023). "Using BEAS-2B cells as a model, we demonstrated that infections by P. multocida isolates from different animals could induce an increase in respiratory epithelial permeability, and this process was also associated with the bacterial activation of HIF-1α–VEGFA signaling." (PMID 36916939, 2023). "HIF-1α accumulation is mandatory in situations of altered energy demand, such as during infection or hypoxia, by adjusting cell metabolism." (PMID 37629565, 2023). "Previous studies indicating that GLUT4 translocation to the membrane is dependent on HIF-1α signaling further supports our conclusion that HIF-1α signaling facilitates infection." (PMID 36814444, 2023). "We demonstrate that SARS-CoV-2 infection limited HIF-1α stabilization and the resultant prosurvival metabolic reprogramming during the early phase of infection." (PMID 37417946, 2023). "This means that HIF-1α expression is highly correlated to fibrosis severity following infection and disease progression." (PMID 38146374, 2023). "High level of HIF-1α in neutrophils before infection enhances reactive nitrogen species (RNS) production, which will lessen the mycobacterial burden." (PMID 36761171, 2022). "In support of this, immunohistochemistry analysis on day 3 post-infection also revealed robust HIF-1a staining within granulomatous lesions induced by Af-beads compared to the N-beads control." (PMID 36275017, 2022). "While HIF-1α activation following IFN-γ stimulation requires nitric oxide, HIF-1α-mediated control in the absence of IFN-γ is nitric oxide-independent, indicating that distinct pathways can activate HIF-1α during infection." (PMID 35877763, 2022). "Starting from 24 h post-infection, we detected increased HIF1α stabilization in hypoxic BMDM infected with the ΔdotA mutant." (PMID 35755850, 2022). "In virally infected animal and cell models, inhibiting the HIF1A pathway can promote the proliferation of reparative macrophages, which is conducive to tissue repair and homeostasis after infection and increase in survival rate." (PMID 35844544, 2022). "Under hypoxia, we observed HIF1α protein accumulation in uninfected cells at 4 and 24 h, which was further augmented by infection with C. burnetii." (PMID 35755850, 2022). "As a central participant in adjusting the immunological response to infection and inflammation, NF-κB is involved in the HIF-1α mRNA transcriptional response and in the downstream signaling of Toll-like receptors (TLRs)." (PMID 36291237, 2022). "Attenuated HIF-1α signaling and impairment of downstream immune responses are theoretical concerns when supplemental O2 is given for patients with infection." (PMID 36035495, 2022). "It is also apparent from our results that in addition to the expression of the PFKFB3 gene, infection of hSMs with the UT127 strain also induced higher levels of HIF1A, HK1, HK2, PDP1, and PDP2 genes compared with the infection with UT205." (PMID 35163725, 2022). "The interrelated roles of AHR and HIF-1α signaling play an important role in the coordination of such processes as infection and inflammatory diseases." (PMID 35327980, 2022). "We also analyzed the expression kinetics of HIF-1α after infection with a strain NADC30-like PRRSV strain, CHN-HB-2018, and similar results were observed." (PMID 36416550, 2022). "HIF-1β is the constitutively expressed subunit, but the expression of HIF-1α is stabilized rapidly in response to hypoxia or infection." (PMID 36416550, 2022). "Glycolysis stabilizes the transcription factor HIF-1α and increases IL-1β expression, linking metabolic and immune responses during infection." (PMID 35531332, 2022).